IFNAR1 (interferon alpha and beta receptor subunit 1)
Diseases named in the same sentence as IFNAR1 in open-access papers (continued):
Sharing a sentence is not in itself a finding about the gene and the disease.
tumor (continued). "Type I IFN and its receptor (IFNAR1/2) also contribute to the immunosuppressive tumor microenvironment." (PMID 29050360, 2017). "In agreement, tumor associated DCs presented higher levels of maturation markers (CD40, CD80 and MHC-I and II molecules) after RT, yet if treatment was performed in an Ifnar1 KO background, therapeutic control was completely lost." (PMID 29050360, 2017). "IFNAR1 can be partially down-regulated by BRAF activation and additional mutations such as in PI3K, can disrupt this balance and abolish the tumor suppressive role of IFN signaling." (PMID 28798748, 2017). "In support of this NS1-mediated inhibition, we observed a reduction in expression of IFNAR1 in ex vivo human non-tumor lung tissues infected with H5N1 and H1N1 viruses." (PMID 28498306, 2017). "This conclusion is based on two key observations: First, Ifnar1 knockout (KO) mice are more tumor-prone upon exposure to the carcinogen methylcholanthrene (MCA) in comparison with mice that have functional type I IFN signaling." (PMID 29050360, 2017). "As MOPC cells express the IFN-α/β receptor subunit 1 (IFNAR1), we analysed LCMV-induced tumour regression in Ifnar−/− mice, which are deficient in the IFN-I receptor." (PMID 28248314, 2017). "While IFNAR1 loss did not accelerate tumor growth, STAT2 deletion consistently suppressed cell proliferation and tumor formation in both human and murine models." (PMID 41440237, 2025). "Nonetheless, the overarching pattern remained consistent: loss of STAT2 suppressed cell proliferation and tumor growth, whereas loss of IFNAR1 did not, underscoring their divergent roles in tumor biology." (PMID 41440237, 2025). "Since IFNAR1/2 molecules are present on both cancer cells and neighboring tumor-infiltrating immune cells, dual anticancer and immune-potentiating activities are potentially achieved in a tumor-directed manner." (PMID 40243928, 2025). "However, in xenograft tumor transplantation models, IFNAR1 KO cells formed larger tumors while STAT2 KO tumor cells formed smaller ones compared to parental tumor cells." (PMID 41440237, 2025). "Furthermore, the anti-proliferative effect of ceralasertib in combination with IFN-β was abrogated by siRNA mediated knockdown of IFNAR1 expression in tumor cells." (PMID 38402224, 2024). "As the lymph nodes play an essential role in cross-presenting antigen to T cells and initiating T cell killing of tumors, we also assessed the maturation and activation of DCs in dLNs after zebularine treatment in B16F10 tumor-bearing wild-type, Cgas-/-, Sting gt/gt, and IFNAR1-/- mice." (PMID 38755254, 2024). "Gene expression mRNA level analysis exhibited significant upregulation of mRNA levels in tumor tissue: IFNAR1 (3.4-fold increase, p < 0.0001), IRF9 (4.2-fold increase, p < 0.0001), STAT1 (7.1-fold increase, p < 0.0001), and IFI27 (66.3-fold increase, p < 0.0001)." (PMID 39457004, 2024). "Moreover, we used B16F10 tumor-bearing IFNAR1-/- mice to examine zebularine-dependent type I interferon signaling in promoting the expression of genes involved in tumor antigen processing and presentation." (PMID 38755254, 2024). "ATP inhibition significantly reduced the therapeutic efficacy of CD47-SIRPα ICB, and ATP administration largely rescued the failed efficacy of CD47-SIRPα ICB in IFNAR1 knockout tumors, suggesting that ATP is a major mediator downstream of tumor cell-intrinsic IFNAR signaling." (PMID 38982116, 2024). "We observed that blockade of IFNAR-1 resulted in a reduced number of oHSV-induced tumor cell death." (PMID 38693119, 2024). "Indeed, our SA knock-in model demonstrated that sustained IFN1 signaling via an IFNAR1 that cannot be downregulated accelerated tumor growth, worsened overall survival, and generated more severe lung metastasis." (PMID 38405101, 2024).
tumor (continued). "In line with this, treatment of mice bearing the Arf1‐ablated tumor cells with anti‐IFNAR1 and anti‐IL‐1β antibodies had markedly reduced frequency of the TNF+IFNg+PD1+CD8+ T cells in tumors in comparison with those in tumors treated with the isotype control antibody." (PMID 37786300, 2023). "Inactivation of the type I interferon (IFN-I) pathway is required for MDSCs in cancer to acquire immunosuppressive activity while stabilizing Interferon Alpha/Beta Receptor 1(IFNAR1) combined with interferon induction therapy elicits a robust anti-tumor effect." (PMID 37443711, 2023). "Moreover, an IFN-I receptor (IFNAR1)-blocking antibody abrogated the anti-tumor effect observed in Usp18Δ/Δ mice." (PMID 38100351, 2023). "Then, we further explored whether IFN-Is affected the efficacy of cisplatin through other non-tumor cells by using IFNAR1 blocking antibody." (PMID 37670034, 2023). "However, compared to the isotype treatment, treatments with systemic anti‐IFNAR1 and anti‐IL‐1β antibodies abrogated anti‐tumor effects, as evidenced by significantly increased tumor size and tumor weight of mice bearing the Arf1‐ablated tumor cells." (PMID 37786300, 2023). "However, all four IFNAR1 knockout tumor models acquired radiosensitivity demonstrated by significantly prolonged survival in vivo." (PMID 36571986, 2023). "The consequences of IFNAR1 depletion have been studied in other tumor entities." (PMID 36571986, 2023). "Furthermore, robust tumor growth persisted in 5 of the 8 mice that we continued to monitor after anti-IFNAR1 treatment was halted on day 12, and only moderate regression was observed in the 3 other mice, despite ongoing CPA treatment." (PMID 36187936, 2022). "Indeed, Ifnar1-/- mice treated with IFN-λ show significantly decreased tumor growth, as compared to untreated Ifnar1-/- mice." (PMID 35833131, 2022). "Naïve non-tumor-bearing WT and Ifnar1-/- mice were used as a control." (PMID 35833131, 2022). "This possibly contributes to the enhanced tumor growth in Ifnar1-/- mice." (PMID 35833131, 2022). "IFNAR1 downregulation contributes to the suppressive tumor microenvironment." (PMID 35301282, 2022). "Conversely, VPS9D1-AS1 OE significantly upregulated the expression of IFNAR1 in tumor cells." (PMID 36458816, 2022). "Notably, significantly more neutrophils accumulated in TDLNs of tumor-bearing Ifnar1-/- mice compared to tumor-bearing WT controls." (PMID 35833131, 2022). "Moreover, the antitumor immunity of the Maraba rhabdovirus is greatly impaired when IFNAR1 is blocked in mouse tumor models, suggesting the Maraba virus is dependent on the type I IFN-mediated anti-tumor immune response." (PMID 35292881, 2022). "Mice receiving the immune modulatory metronomic cyclophosphamide schedule had a significant increase in tumor optical scattering compared to mice receiving cyclophosphamide in combination with the IFNAR-1 antibody (9% increase vs 10% decrease on day 5 of treatment, p < 0.001)." (PMID 35393476, 2022). "However, tumor-bearing Ifnar1-/- mice show significantly less T-cell interactions per neutrophil in comparison to WT mice." (PMID 35833131, 2022). "Importantly, we observed that IFN-λ treatment of tumor-bearing Ifnar1-/- mice led to a significant increase of neutrophil/T-cell interactions in TDLNs of these mice, to the levels observed in WT mice." (PMID 35833131, 2022). "Deactivation of type I IFN receptor (IFNAR1) on neutrophils leads to a significant reduction of neutrophil/T-cell interactions accompanied by the decreased activity and proliferation of the T cells, and elevated tumor growth in such mice." (PMID 35833131, 2022). "However, expression of IFNAR1 was required to prevent this conversion and led to the inactivation of tumor-suppressive activities." (PMID 33741967, 2021).
tumor (continued). "Proteolytic loss of IFNAR1 in the nonimmune tumor microenvironment promotes a stable activation of CAFs and enhances tumor growth, whereas stabilization of the receptor attenuates the pro-tumorigenic phenotype of CAFs." (PMID 33920230, 2021). "Therefore, we tested the effect of tumor-derived factors on IFNAR1 expression by exposing mouse PMN or Mon to the tumor explant supernatant (TES) obtained from different EL-4 tumors." (PMID 33741967, 2021). "Similar results were obtained with selective p38 inhibitor, strongly suggesting that p38 activation in response to diverse tumor-derived factors may be a major mechanism that regulates IFNAR1 expression in MDSC." (PMID 33741967, 2021). "Interestingly, knock-down of IFNAR1 in tumor cells completely abolished the therapeutic effects of this hypofractionated RT, indicating an indispensable role of tumor IFNAR1 expression in this system." (PMID 34830176, 2021). "Deletion of the Tlr9 or Ifnar1 gene rendered the vaccine ineffective in blocking tumor formation." (PMID 34194942, 2021). "All of the tested receptors were expressed in tumor cells, the most abundant being Ifnar1." (PMID 33202881, 2020). "These could include for example testing other tumour derivations such as the well-studied B16 with IFNAR1−/− knockout or the use of oncolytic viruses other than VSV-GP." (PMID 31530903, 2019). "Naïve, age-matched animals developed LLC1 wt or IFNAR1−/− tumours within 8 days." (PMID 31530903, 2019). "In tumor tissue, elevated neutrophil infiltration was observed in Ifnar1-/- mice." (PMID 31717318, 2019). "Moreover, the therapeutic outcome of a PD-1 blockade was influenced by tumor cell expression of IFNAR1." (PMID 31481761, 2019). "Of note, steady-state suppressive capacity of MDSC was significantly less-pronounces in IFNAR1-deficient hosts; thus, it is tempting to speculate that early- and late-stage IFN signaling share a causal relationship in MDSC development and tumor control." (PMID 31694706, 2019). "In order to examine whether IFN-receptor in tumor cells is required for IFNα induced tumor killing, we knocked out IFNAR1, and found that IFNα-anti-PD-L1 continued to efficiently control tumor growth in mice bearing IFNAR1-/- A20 tumors." (PMID 30389912, 2018). "In this context, it has been demonstrated that in vitro and in vivo inactivation of IFN signaling by using shIFNAR1 cells and IFNAR1-null mice, respectively, overcomes oncogenes-induced senescence, a tumor suppressive signal that protects DNA damaged cells from the onset of cancer." (PMID 28798748, 2017). "Similarly, rejection of the irradiated and abscopal MCA38 tumours in mice treated with 8GyX3+anti-CTLA4 was abrogated in IFNAR1−/− mice." (PMID 28598415, 2017). "Furthermore, BALB/c mice bearing subcutaneous tumours in which IFNAR1 was knocked-down, showed that Sinbis virus infection significantly retarded tumour growth." (PMID 27367734, 2016). "Although IFNAR1 is generally not considered a tumor suppressor, IFNAR1-deficient MEFs spontaneously immortalize in culture at a higher rate than normal MEFs, suggesting an important role of IFN-I signaling in tumor suppression." (PMID 27809273, 2016). "IFNAR1 has recently been proposed as a novel candidate CRC tumor suppressor gene." (PMID 25350395, 2014). "Since inter-individual variations in the expression of IFNAR mRNAs may be important, the relative yield of the PCR product from the tumor to that from the corresponding non-tumor tissue (T/N) for expression of IFNAR1 and IFNAR2 was calculated as previously." (PMID 17697365, 2007). "In contrast, depletion of IFN-β and anti-IFNAR1 antibody treatment almost completely reversed tumor regression mediated by ASNS knockdown in syngeneic mice, suggesting that other types of immune cells besides CD8+ T cells might also contribute to ASNS loss–triggered antitumor immunity." (PMID 39964752, 2025).
tumor (continued). "We found that Cdk4−/− tumor could grow at a similar rate as vector cells and Cdk6−/− tumor could grow to bigger size in Ifnar1−/− mice than those in WT C57 mice, suggesting the important role of IFNAR-1 in TME for the anti-tumor immunity activated in Cdk4−/− and Cdk6−/− cancer cells." (PMID 37833461, 2023). "To test this hypothesis, we subcutaneously inoculated BALB/c mice with the control or Arf1‐ablated CT26 cells, and then administrated mice with anti‐IFNAR1 and anti‐IL‐1β antibodies or isotype control antibodies at day 0, 2, and 4 after tumor cell injection, respectively." (PMID 37786300, 2023). "Taken together with the finding that Ifnar1-deficient mice treated with β-glucan failed to train granulopoiesis to repress tumor growth, these results suggest that β-glucan promotes anti-tumor activity through epigenetic changes in granulopoiesis that are dependent on IFN-I signaling." (PMID 35883630, 2022). "However, IFNAR1 downregulation was higher in tumor MDSC than in spleen MDSC." (PMID 33741967, 2021). "Furthermore, our data indicated that tumor-derived factors-driven p38 kinase-dependent downregulation of IFNAR1 represents a mechanism, by which this role of the IFN1 pathway in myeloid cells is overwhelmed during tumorigenesis leading to the acquiescence of immune-suppressive activities." (PMID 33741967, 2021). "However, the observed IFNAR1-dependent alterations in immune cell activation, which also included a profound T cell activation, are characteristic for the transition of a “cold” towards a “hot” tumor." (PMID 31694706, 2019). "Its depletion elevated extracellular cGAMP, expanded anti-tumor immune cells (M1 macrophages, cDC1s, and cytotoxic T cells), reduced Tregs, and induced a STING- and IFNAR1-dependent type I interferon signature in macrophages." (PMID 41715305, 2026). "The requirement of host response to IFN-I for the augmentation of tumor regression and T cell responses by CTX treatment was demonstrated in previous studies using IFNAR1 blockade with antibody and Ifnar1−/− mice, respectively." (PMID 40227734, 2025). "To further determine if the interferon signaling pathway is involved in MTX-mediated anti-tumor effects in Cdk2-/- tumors, we treated C57 mice carrying Cdk2-/- MCA205 tumors with antibodies that neutralize IFNAR1." (PMID 40557162, 2025). "Immune evasion was evident through upregulation of NFKB1, IFNAR1, TLR4, IL1A/B/R1, and NOS2, facilitating tumour escape from immune surveillance." (PMID 41007296, 2025). "In vivo, NLRX1-mediated inhibition of anti-tumor immunity was IFN-I-dependent, which was evidenced by the comparable levels of tumor volumes and STING signature genes between groups in Ifnar1–/– hosts." (PMID 41142804, 2025). "IFNGR1/2 and IFNAR1, serving as the receptor for IFN-γ and IFN-α respectively, are critical in cancer cell fate and tumor microenvironment." (PMID 40708945, 2025). "The therapeutic tumor cells were derived from CT2A cells and genetically edited using CRISPR/Cas9 to knock out IFNAR1 and were engineered to express IFN-β." (PMID 39560995, 2024). "While defects in MMR reduced in vivo tumor growth in comparison to wild-type tumor cells, concomitant deletion of tumor cGAS, STING, or IFNAR1 rescued these growth defects, indicating a key role of cGAS/STING-type I IFN axis in immune surveillance." (PMID 39544936, 2024). "In mouse syngeneic tumor models, genetic ablation of the IFN-alpha receptor (IFNAR1) in DCs demonstrated that type I IFN signaling in DCs, and particularly the cDC1 subset, is required for IFN’s anti-tumor activity." (PMID 37942313, 2023). "Emerging evidence shows that the downregulation of the IFNAR1 chain is found in MDSC from cancer patients and mouse tumor models." (PMID 37006306, 2023). "Consistent with the notion that CD4+ T cells are critical for NEC immunization-mediated tumor control, CD4+ T cell infiltration was reduced in Ifnar1−/− mice compared to WT controls." (PMID 38196632, 2023).
tumor (continued). "Conversely, tumor cells overexpressing VPS9D1-AS1 were resistant to CD8+ T cell killing and lowered IFNAR1 expression in CD8+ T cells." (PMID 36458816, 2022). "In our studies, we consistenly observed higher frequency of PD-1+ cells in tumor infiltrating CD4+ and CD8+ T cells when IFNAR1 was blocked." (PMID 36311701, 2022). "These tumor cell-centric ISG responses to activated CPA were at least in part dependent on signaling by the type I IFN receptor, IFNAR1, implicating tumor cell production of type I IFNs in these drug-induced ISG responses." (PMID 36187936, 2022). "In contrast, E0771 tumors exhibited a somewhat weaker IFN response, but this was followed by robust immune infiltration and extensive tumor regression, both of which were absolutely dependent on type-I IFN signaling by IFNAR1." (PMID 36187936, 2022). "Gene expression analysis showed that anti-IFNAR1 antibody reduced ISG expression below control tumor levels by day 12, indicating the antibody is highly effective in blocking tumor IFN signaling." (PMID 36187936, 2022). "Downregulation of the IFNAR1 chain of this receptor is found in MDSC from cancer patients and mouse tumor models." (PMID 33741967, 2021). "Further, it was found that TME of CRC induced a dramatic downregulation of IFNAR1 on CD8+ TILs and transferred CAR-T cells, leading to impaired survival of these cells and dampened anti-tumor responses of CAR-T and anti-PD-1." (PMID 34830176, 2021). "IFNAR1 KO CAR T cells were partially resistant to the VSVmIFNβ induced attrition in vivo and provided improved tumor control in a combinatorial setting." (PMID 32581235, 2020). "4T1 tumor-bearing mice were randomly grouped and treated with PBS, siRNA2@HPVP plus IgG, siRNA2@HPVP plus anti-IFNAR1 antibody, and siRNA2@HPVP, respectively." (PMID 32332752, 2020). "Together, although overexpression of IFNAR1 correlated with worse prognosis of HNSCC, activation of IFNα signalling was also evident as manifested by MX1 expression in tumour microenvironment of HNSCC." (PMID 30555157, 2019). "To understand how abrogation of type I IFN signaling in cancer cells led to better tumor control, we characterized CD8+ T cells in tumors from WT or Ifnar1-KO MC38 tumors after IR." (PMID 31483286, 2019). "Overexpression of IFNAR1, MX1 and signal transducer and activator of transcription 1 (Stat1) indicated the endogenous IFNα activation in tumour microenvironment, which correlated with immunosuppression status in HNSCC patients." (PMID 30555157, 2019). "The level of IFNAR1 mRNA was also higher in 4/5 HNSCC cell lines than that in the control cell line, and the protein level of IFNAR1 was also increased in the tumour tissues compared with that in the adjacent normal tissues in 4/5 HNSCC patients." (PMID 30555157, 2019). "Down-regulation of IFNAR1 in immune and tumor cells as a mechanism of resistance to IFN in cancers has, perhaps deservedly, garnered most interest in this context as cell surface IFNAR1 levels are key for type I IFN anti-proliferative effects." (PMID 30186768, 2018). "The protein expression of IFNAR1 was significantly correlated with those of IRF1 and PDL1 in both tissues but with those of ATF4 and eIF2α only in the tumor tissue." (PMID 30305853, 2018). "The protein level of IRF7 was correlated only with that of STAT2 in the tumor tissue but with those of molecules other than STAT2 and IFNAR1 in the normal tissue." (PMID 30305853, 2018). "Rejection of the irradiated and abscopal TSA tumours in mice treated with 8GyX3+anti-CTLA4 was abrogated in Batf3−/− and interferon-α/β-receptor-1 (IFNAR1)−/− mice, demonstrating the requirement for CD8α+ TIDCs responsive to IFNβ." (PMID 28598415, 2017). "Based on their functions, the literature and their occurrence within the candidate deleted FMCR, we propose RASSF3, IFNAR1, IFNAR2 and NFKBIA as novel candidate CRC tumour suppressor genes." (PMID 24367615, 2013).